H19 (H19 imprinted maternally expressed transcript)
Diseases named in the same sentence as H19 in open-access papers (continued):
Sharing a sentence is not in itself a finding about the gene and the disease.
cancer (continued). "Angiogenesis inhibitors are used in the treatment of cancer pointing to H19 as a potential target in this example." (PMID 28933364, 2017). "H19 is a highly abundant, conserved, and imprinted lncRNA that is overexpressed in several cancers and acts as an oncogene, promoting tumorigenesis and cancer progression." (PMID 27926484, 2017). "Meanwhile, LncRNA H19 has been considered as a vital player in cancer development, not only because the alteration of H19 expression is frequently observed, but also it actively participates in a wealth of malignancies and almost all stages of tumorigenesis." (PMID 28230721, 2017). "H19 RNA is highly expressed in various cancers and plays a proto-oncogenic function in several tumors." (PMID 28367967, 2017). "Hypoxia also induces LncRNA H19, which is involved in hypoxia-induced signal transduction processes in cancer cells, thereby altering glucose metabolism." (PMID 28738810, 2017). "H19 is an imprinted oncofetal lncRNA aberrantly expressed in various cancer types with multifaceted roles throughout tumorigenesis." (PMID 28872613, 2017). "This example highlights how H19 is regulated differently between different cancers and cell types, as well as the need to focus on H19 in the context of HCC." (PMID 28933364, 2017). "Together, these results suggest that the H19/SAHH/DNMT3B axis is active in multiple cancer types, where it can mediate metformin-induced hypermethylation of H19." (PMID 27775072, 2017). "As an example, H19 has been verified to function positively in some cancers but negatively in other cancers, and in myoblast differentiation, H19 exhibits several mechanisms for the same promoting effect." (PMID 28652859, 2017). "The lncRNA H19 is another well-known oncogene in various cancer types, tumorigenesis, and cancer progression." (PMID 28467794, 2017). "In the future, further studies with larger samples are required to ascertain the prognostic significance of H19 expression in cancers, especially in female cancers." (PMID 27926484, 2017). "In thyroid cancer, H19 promotes proliferation, migration, and invasion of cancer cells through the sponging of miR-17-5p." (PMID 29099749, 2017). "Our current study and previous publications have suggested that expression of H19 was cancer cell specific." (PMID 29273733, 2017). "The implication of H19 and 91H in cancer is well described and is mediated by different mechanisms characteristics of that observed for other non-coding RNAs." (PMID 29099749, 2017). "High levels of H19 often correlate with poor prognosis for cancer patients, and with the development of chemoresistance in various cancers, including ovarian (cisplatin), colorectal (methotrexate), liver (doxorubicin) lung (cisplatin), and breast (paclitaxel)." (PMID 29299178, 2017). "The H19 gene, which is a paternally imprinted onco-fetal gene, is typically down-regulated in adult tissues, but can be expressed in cancer tissues at levels similar to those observed in fetal life." (PMID 28404885, 2017). "Recent studies have demonstrated that lncRNA H19 plays important roles in carcinogenesis and cancer metastasis." (PMID 28404885, 2017). "It has been reported that H19 upregulation is linked to the EMT process in carcinogenesis and embryogenesis, and induction of EMT by different approaches (e.g., hypoxia, TGF-β) in cancer cells is accompanied by H19 upregulation." (PMID 29062612, 2017). "In these 38 included articles, we observed that a variety of lncRNA genes had been investigated the association with cancer risk, among which lncRNA HOTAIR, PRNCR1, H19, and POLR2E had been widely studied." (PMID 28159929, 2017). "Herein, we conducted a meta-analysis to summarize all eligible case-control studies to evaluate the overall cancer risk and common lncRNAs (HOTAIR, PRNCR1, H19, and POLR2E) polymorphisms." (PMID 28159929, 2017). "Such a feedforward mechanism would help to reinforce metformin's action on H19 repression in cancer cells." (PMID 27775072, 2017).
cancer (continued). "This H19 overexpression was contributed to cancer cell resistance to anthracyclines and paclitaxel as knockdown of H19 lncRNA by a specific H19 shRNA in Dox-resistant cells significantly improved the cell sensitivity to anthracyclines and paclitaxel." (PMID 29190892, 2017). "In recent years, there have been a growing number of reports on the biological functions of H19 in cancers, but few studies on the prognostic significance of H19 expression in cancers, especially female cancers." (PMID 27926484, 2017). "Induction of epithelial-mesenchymal transition (EMT) in cancer cells due to aberrant H19 expression can promote pancreatic ductal adenocarcinoma cell invasion and migration." (PMID 27027436, 2016). "For example, the TF E2F1, the lncRNA H19 and the miRNA miR-106 had high degrees and were dysregulated in many types of cancer." (PMID 27322142, 2016). "Our results further demonstrate the cancer-promoting role of H19 in GSCs and help expand the existing knowledge from CD133+ GBM cells to ones bearing four different stem cell markers." (PMID 26983719, 2016). "The expression of lncRNA H19 has been reported in various cancers, where H19 is thought to take part in tumorigenesis and metastasis." (PMID 27845892, 2016). "In contrast to other lncRNAs, H19 has already been found to be a promising target for gene therapy in various types of cancer." (PMID 27092491, 2016). "Meta-analysis has also revealed that a high expression of H19 is significantly related to lymph node metastasis, another influence on cancer prognoses." (PMID 27732938, 2016). "The high expression level of H19 was considered to be correlated with diverse human disorders and cancers." (PMID 27825121, 2016). "The upregulation of H19 in cancer tissues suggests its possible tumorigenic properties, although the detailed molecular mechanism remains to be investigated." (PMID 26872375, 2016). "H19 is an oncogenic lncRNA that is highly expressed in many cancers and has roles in EMT, cell migration and angiogenesis." (PMID 26590207, 2016). "H19 is up-regulated in several types of cancer, including breast, bladder, ovarian and gastric cancer, as well as glioma." (PMID 27092491, 2016). "Loss of IGF2 or H19 imprinting leads to IGF2 upregulation and subsequent H19 promoter hypermethylation, a phenomenon commonly found in cancers." (PMID 26989421, 2016). "Long non-coding RNA (lncRNA) H19 has been reported to involve in many kinds of human cancers and functions as an oncogene." (PMID 27716361, 2016). "Another lncRNA, H19 has recently been identified as an oncogene aberrantly expressed in multiple cancer types." (PMID 26978351, 2016). "The involvement of H19 in maintenance of stem cell markers has been reported in other types of cancer before." (PMID 26983719, 2016). "On the other hand, a cancer-promoting role of H19 has been suggested in colorectal and gastric cancers." (PMID 26989421, 2016). "Well-conducted studies with larger sample sizes are needed to further explore the cancer risks related to H19 SNPs, especially in Caucasians." (PMID 27732938, 2016). "The overexpression of H19 in cancer tissue hints for its oncogenic function, but the exact underlying mechanism is still not clear." (PMID 26989025, 2016). "H19, a maternally expressed imprinted gene transcribing a long noncoding RNA, has previously been reported to be involved in tumorigenesis and cancer progression." (PMID 26886624, 2016). "The functional translation of this important molecular event is the ability of H19 /miR-675 to enhance cancer cell invasion in vitro and metastasis in vivo." (PMID 26623562, 2016). "Several well-studied lncRNAs have been considered as potential targets or powerful predictors in cancers, such as Linc00668, H19 and UCA1." (PMID 27863388, 2016).
cancer (continued). "H19 has been found to be highly expressed in mesenchymal-like cancer cells and is believed to promote epithelial to mesenchymal transition by functioning as a miR sponge that primarily affects miR-138 and miR-200a." (PMID 26978351, 2016). "In light of the growing body of evidence showing H19/miR-675's involvement in the two pathways, this axis should stand as a first priority target for cancer therapy." (PMID 26623562, 2016). "And the increased expression of H19 in cancer tissues was frequently positively correlated with advanced clinical stage and inversely correlated with patient's prognosis." (PMID 27825121, 2016). "Whereas TGF-β induced H19 expression in cancer cells resulted in EMT, its suppressive effect on H19 expression in normal cells remain to be elucidated." (PMID 26623562, 2016). "Our recent observations show that TGF-β can induce the level of H19/miR-675 along with established EMT markers in various carcinoma models." (PMID 26623562, 2016). "The authors, indeed, have shown that H19 expression is significantly lower in invasive HCC cancers compared to noninvasive tumors and that H19 expression positively correlates with miR-200b expression." (PMID 25861629, 2015). "H19 is increasingly described to play key roles in the progression and metastasis of cancers from different tissue origins." (PMID 26353930, 2015). "H19 is expressed at high levels in cancer cells and increased H19 expression is found in some cancers.e.g." (PMID 26376677, 2015). "In adult tissues, H19 expression is retained in muscles (skeletal muscles and the heart), or is suddenly activated in cancers, where it is believed to act mainly as an oncogene." (PMID 25774169, 2015). "In view of its deep involvement in cancer, H19 should be placed in the center of the combat against cancer as a main therapeutic target and a cancer marker." (PMID 26536864, 2015). "Rising evidence showed that H19 was upregulated in diverse cancer types including CRC, esophageal cancer, bladder cancer, breast cancer, and hepatocellular carcinoma." (PMID 26068968, 2015). "The overexpression of H19 in cancer patients highlighted its tumorigenic properties, while the detailed molecular mechanisms remain poorly understood." (PMID 26068968, 2015). "For example, metastasis-associated lung adenocarcinoma transcript 1 (MALAT1), prostate cancer associated non-coding RNA 1 (PRNCR1), prostate cancer gene expression marker 1 (PCGEM1), H19, and several new lncRNAs involve in glioma development." (PMID 26172293, 2015). "Several cancer-promoting genes were uperegulated (Ctgf, H19, Mmp12, Mybl1, Vnn1) while cancer inhibiting genes (Cish, Dkk4, Onecut1, Scara5, Socs3, Wif1) were suppressed." (PMID 26200659, 2015). "We further explored the biological significance of H19 rs217727 and rs2839698 by examining the correlations between rs217717 and rs2839698 genotypes and expression levels of H19 mRNA in serum samples from 80 cancer-free controls." (PMID 25944697, 2015). "It is becoming increasingly clear that H19 and miR-675 are key players in many human cancer types including those of the lung." (PMID 25884481, 2015). "miR-675 is processed from H19 lncRNA, but both are up-regulated in many types of cancers and both can be up-regulated by common triggers." (PMID 25884481, 2015). "H19 and the core stemness transcription factors were shown to be overexpressed in several other cancers such as Bladder, Lung, Liver, Breast, Ovary and Prostate." (PMID 26415227, 2015). "Our results are supported by studies reporting that the increase of H19 expression in cancer cells contributed to the proliferation of cancer." (PMID 26415227, 2015).
cancer (continued). "For example, H19 is a long non coding RNA upregulated by the proto-oncogene MYC, elevated in a wide range of cancers and associated with risk factors such as exposure to carcinogens." (PMID 26200659, 2015). "In HCC, however, to date, only a few studies implicated lncRNAs, such as MALAT1, HOTAIR, HOTTIP/HOXA13, H19, HULC, MEG3, in the cancer pathogenesis." (PMID 25686840, 2015). "As previously discussed for H19, many lncRNAs can themselves serve as precursors for miRNAs, some of which are known to play important roles in cancer progression (mechanism 4)." (PMID 24346158, 2014). "A multi-cancer study also found that H19 expression was significantly higher in liver metastases compared to the primary tumors from which they originated." (PMID 24346158, 2014). "More important, in mouse myoblasts, 91H was determined to be implicated in co-regulation of genes at the H19/IGF2 locus contributing to carcinogenesis and cancer progression." (PMID 25058480, 2014). "Induction of EMT in cancer cells by different approaches (e.g., hypoxia, TGFβ) is accompanied by H19 upregulation." (PMID 23429271, 2013). "Apart from cancer, H19 expression has been reported also in other conditions, syndromes and diseases, where deregulated imprinting at the H19 locus was obvious in some cases and will be summarized below." (PMID 23429271, 2013). "Based on the pivotal role of the H19 gene in human cancers, we have developed a DNA-based therapeutic approach for the treatment of cancers that have upregulated levels of H19 expression." (PMID 23429271, 2013). "Recent data on bladder cancer documented how upregulated H19 increased cancer cell proliferation by increasing inhibitor of DNA binding 2 (ID2) expression." (PMID 23860209, 2013). "We also observed a substantial alteration in chromatin structure within human cancers that have lost IGF2 imprinting, resulting in a striking loss of long-range interactions across the IGF2/H19 locus." (PMID 24019942, 2013). "From the lncRNA expression profiles obtained from lncRNA microarray analysis, we found that among the significantly different expressed lncRNAs, only H19 has been found in other cancers." (PMID 24063685, 2013). "For example, lncRNA-H19 level is remarkably elevated in a large number of human cancers, and H19 overexpression confers a growth advantage on cancer cells." (PMID 24069260, 2013). "To obtain more information about H19 expression in cancers, we investigated its level in some common cancer cell lines." (PMID 24063685, 2013). "Following our initial study showing H19 induction upon hypoxia in certain cell lines, we screened about thirty different carcinoma cell lines of different lineages and origins for their ability to induce H19 RNA in hypoxic stress." (PMID 23429271, 2013). "Our group previously reported the use of a new DNA-based therapy for cancer treatment in which the plasmid BC-819 (also known as DTA-H19) drives the expression of diphtheria toxin A chain by the regulatory sequence of the H19 gene only into cancer cells." (PMID 22701803, 2012). "In tissue specimens, hypermethylation at the H19 DMR is also frequent in cancers of the ovary, breast, esophagus, and prostate." (PMID 22392079, 2012). "The numbers of cancer tissue cases with hypermethylation above the range of the methylation rates in the normal ovarian surface epithelium were 17 for H19, 21 for GTL2, 21 for ZDBF2, and 14 for PEG1." (PMID 22443985, 2012). "The CTCF binding sites (P1, P2, and P3) in the H19 DMR are sensitive to methylation changes in cloned porcine genomes or human cancers." (PMID 22393450, 2012). "Aberrant DNA methylation at the IGF2 and neighboring H19 DMRs has been associated with deregulated IGF2 expression, childhood cancers and several chronic diseases during adulthood." (PMID 22414206, 2011).
cancer (continued). "H19 is upregulated in a number of human cancers, including hepatocellular, bladder and breast carcinomas, suggesting an oncogenic function for this lncRNA." (PMID 21489289, 2011). "According to this approach patients will be treated with specific double promoter expression toxin vector which are under the control of the IGF2-P4 and H19 regulatory sequences, differentially expressed in those cancers." (PMID 21162716, 2010). "A superior activity of the double promoter vector in lysing the cancer cell lines was exhibited, relative to the combined activity of both single promoter constructs (H19-DTA + IGF2-P4-DTA), in a dose response manner." (PMID 21162716, 2010). "The double-promoter construct H19-DTA-P4-DTA exhibited enhanced efficiency in lysing the cancer cell lines, relative to the combined activity of both single promoter constructs (H19-DTA + P4-DTA), in T24P cells." (PMID 21162716, 2010). "Over plurality of cancer specific promoters, H19 and IGF2-P4 regulatory sequences were selected for targeting cancer cells." (PMID 21162716, 2010). "Our group previously reported the use of DNA-based therapy for cancer treatment which drives the expression of diphtheria toxin A chain by the regulatory sequence of the H19 gene only into cancer cells." (PMID 21052499, 2010). "The H19 gene is an oncofetal RNA expressed during embryo development and in several types of cancer." (PMID 21052499, 2010). "Transcription of IGF2 and H19 is developmentally down regulated in most adult tissues but reactivated in various cancers." (PMID 19956766, 2009). "Epigenetic alterations of H19 or LIT1, which encode untranslated RNAs on 11p15, are strongly associated with cancer risk or specific birth defects in BWS." (PMID 19737423, 2009). "Based on earlier studies from our group and others, transcriptional regulatory sequences of the H19 gene have emerged as candidates for cancer gene therapy." (PMID 19656414, 2009). "The list of cancers in which H19 gene expression is known to be elevated compared to normal tissue is still growing." (PMID 19656414, 2009). "At least 50 genes in our list are already known to be regulated by DNA methylation, such as those encoding cancer antigens (a set of MAGE and GAGE), H19, S100A4, IGFBP4, UCHL1, COL1A2, CLU, FN1, and TGFBI." (PMID 19234609, 2009). "IGF2 and H19 are closely linked and reciprocally imprinted, and epigenetic alterations in human cancers at an intergenic differentially methylated region (DMR) are associated with LOI of IGF2 and silencing at H19." (PMID 15798773, 2005). "The H19/miR-675 axis participates in the occurrence and metastasis of cancers." (PMID 40034562, 2025). "H19 promotes cancer cell migration and can serve as a potential biomarker for BC diagnosis." (PMID 40313963, 2025). "Adeno-associated virus (AAV)-mediated delivery holds promise for DMD therapy, supported by precedents in other diseases where AAV vectors delivered lncRNAs like H19 (cancer), Malat1 (vascular disease), and Neat1 (neurological disorders) to achieve therapeutic effects." (PMID 40649811, 2025). "LncRNAs such as MIAT, SNHH16, LUCAT1, OIP-AS1, MALAT-1, GAS5, and H19, which regulate functions that might disrupt different steps of the cancer–immunity cycle, have been found in EVs." (PMID 40429961, 2025). "The study also showed that metformin, an anti-diabetic medicine, might reduce cancer cells' ability to migrate, in part because of hypermethylated impacted H19 downregulation." (PMID 39912983, 2025). "H19 lncRNA can function by targeting miR-29b-3p, leading to downstream target signal transduction and inhibition of transcription activating factor 3, resulting in carboplatin resistance in cancer cells." (PMID 40191723, 2025). "Similarly, H19 acts as a ceRNA for miR-141, a microRNA that suppresses cancer stemness by targeting the WNT/β-catenin pathway." (PMID 40781643, 2025).